MMP9 (matrix metallopeptidase 9)
Diseases named in the same sentence as MMP9 in open-access papers (continued):
Sharing a sentence is not in itself a finding about the gene and the disease.
Stroke (continued). "Compared to sham controls, stroke resulted in a sharp increase in MMP-9 mRNA and protein levels in the ischemic cortex, which was significantly reduced by dBET1." (PMID 35761277, 2022). "In contrast, MG6 was defined as the “neutrophil-like” subset, with upregulated expression of Cxcr2, S100a8, Il1b, and Mmp9, perhaps representing a stroke-specific state of microglia in the aged brain after stroke." (PMID 36052339, 2022). "Previous reports suggested that certain miRNAs regulate matrix metalloproteinase-9 (MMP-9) expression during stroke." (PMID 36009063, 2022). "Treatments with resveratrol and EGCG have been shown to attenuate Aβ1–40 and slow cognitive decline in AD patients, and in stroke patients, reduce the levels of matrix metalloproteinase-9 (MMP-9) and matrix metalloproteinase-2 (MMP-2)." (PMID 35204290, 2022). "The levels of CD147 in the brain positively correlated with MMP-9 and secondary hemorrhage in post-mortem stroke patient samples." (PMID 34711943, 2022). "MMP-9 is linked to increased BBB disruption and can lead to poorer stroke outcomes in older patients due to increased peripheral immune cell activation." (PMID 34711943, 2022). "Repeated-measures analysis of covariance revealed that, over the acute stage of stroke, serum MMP-9 levels showed substantial increases in the poor prognosis group, which were significantly different from the good prognosis group (P = 0.027)." (PMID 36092813, 2022). "A recent animal study on stroke revealed increased mitochondrial MMP-9 activity and decreased TIMP-2 expression after ischemic cerebral infarction." (PMID 36142283, 2022). "High levels of MMP-9 can be detected in necrotic brain tissue and the ischemic penumbra following a stroke." (PMID 36127663, 2022). "In stroke, biphasic BBB breakdown is caused by activated matrix metalloproteinase (MMP)-2, MMP-3 and MMP-9." (PMID 36224611, 2022). "We report here that the stroke triggered stimulation of the SPAK–NKCC1 complex, NF-κB cascade as well as MMP9 protein expression in the CPECs, which is associated with degradation of TJ proteins and dysfunction of the ChP blood–CSF barrier." (PMID 35413993, 2022). "Increased expression and activity of MMP-9 are observed when the brain suffers from injury or diseases, such as cerebral ischemia, stroke, Alzheimer’s disease, or cancer/tumor metastasis." (PMID 35054789, 2022). "Particularly, MMP-9 can disrupt tight junction proteins and extracellular matrix, causing BBB damage and HT in stroke models." (PMID 35477576, 2022). "Studies involving human patients with stroke have demonstrated that high plasma MMP-9 levels before treatment are more likely to result in cerebral hemorrhage complications after rt-PA therapy." (PMID 35910391, 2022). "Blocking CD147 with an antibody reduced brain hemoglobin and MMP-9 levels in mice 3 days after stroke and reduced infarct size and behavioral deficits." (PMID 34711943, 2022). "Together, this data suggests that NF-κB and MMP9 signaling pathways are activated in ChP after stroke and play a role in damaging the blood–CSF barrier." (PMID 35413993, 2022). "Although MMP-9, which has a destructive effect in the early phase, is upregulated in the peri-infarct cortex 7-14 days after stroke and shows a angiogenesis-promoting function." (PMID 35281064, 2022). "MMP-9 levels also correlated with larger infarct volume, increasing severity of stroke, and poor functional outcome." (PMID 35563537, 2022). "Double immunohistochemistry was performed to determine MMP-9 expression in the brain at 24 h after stroke." (PMID 35309561, 2022). "For example, elevated matrix metalloproteinase-9 (MMP-9) levels are associated with hemorrhagic transformation, and elevated levels of endothelin-1 predict severe cerebral edema in stroke patients treated with rt-PA." (PMID 34398910, 2021).
Stroke (continued). "The results demonstrated that tPA infusion increased MMP-9 expression in the brain of stroke mice, while addition of QSYQ at 0.5 g/kg blocked the increase of MMP-9 expression." (PMID 35095486, 2021). "Neutrophils and brain tissue are major sources of matrix-metalloproteinase-9 (MMP-9) within the first 18–24 h after stroke." (PMID 34917010, 2021). "Elevated MMP‐9 levels have further been reported in several other severe conditions such as severe brain injury and stroke." (PMID 31932967, 2021). "Although MMP-9 inhibition has been proposed as a therapeutic strategy to attenuate BBB breakdown after cerebral ischemia, animal studies showed that MMP-9 is required for neurovascular remodeling and adaptation in the chronic phase after stroke." (PMID 34566627, 2021). "These key circRNAs were associated with a large range of key functional genes involved in ischemic injury, such as HIF-1, Bcl-2, and MMP-9, in response to stroke through the adsorption of miRNAs and the regulation of target genes." (PMID 34868302, 2021). "Particularly in diabetic stroke, MMP9 contributes to aggravated white matter injury and worse stroke outcome." (PMID 33346402, 2021). "Delayed tPA treatment (beyond 4.5 hr post-stroke) is paralleled with complications including hemorrhagic transformation, free radical production, up-regulation of MMP-9, blood-brain barrier (BBB) leakage, and neurovascular cell death." (PMID 35432799, 2021). "Degranulation products like matrix metalloproteinase-9 (MMP-9) and myeloperoxidase (MPO) are generally considered to be associated with the presence of hemorrhage and poor function outcomes after stroke." (PMID 34322078, 2021). "To date, many researchers have regarded MMP-9 as an important target for the treatment of stroke, CI, cardiomyopathy, and other ischemic diseases." (PMID 34594389, 2021). "One study showed that CKLF1 inhibition alleviated MMP9 activity, ZO-1, and occludin disruption, as well as EB leakage after stroke." (PMID 34248961, 2021). "As BBB disruption caused by the degradation of tight junction proteins after stroke was mainly mediated by MMP-9, and inflammatory cytokines were considered to be the main activators of MMP-9." (PMID 34182541, 2021). "Aged mouse stroke brains show that hNSC administration reduces MMP-9 following delayed tPA treatment, suggesting BBB protection." (PMID 34299322, 2021). "Blood substitution therapy profoundly improved stroke outcomes through the robust reduction of neutrophil, cytokine storm, and MMP-9 production." (PMID 34248961, 2021). "Patients with Alzheimer’s disease, multiple sclerosis, amyotrophic lateral sclerosis, stroke, spinal cord injury, or epilepsy are known to have increased MMP-9 and MMP-2 levels in the central nervous system." (PMID 34769297, 2021). "It was also found that changes in BBB permeability were in accordance with the increased level of MMP9 in traumatic brain injury and stroke." (PMID 34759791, 2021). "Analysis of matrix metallopeptidase 9 expression in the brain showed elevated levels after stroke and infection compared to stroke alone indicating augmented vascular injury and blood−brain barrier damage in chronically infected animals." (PMID 34078488, 2021). "Compared with historical controls, RP-1127 also reduced MMP-9 levels at 48 h post-stroke onset as measured by quantitative sandwich ELISA (54 ± 17 ng/mL vs. 212 ± 151 ng/mL, p < 0.01) and pro-MMP-9 enzyme levels (as measured by zymography; p < 0.01)." (PMID 34769328, 2021). "The time distribution of MMP-9 after intracerebral hemorrhage was similar to that after stroke/reperfusion, suggesting that the increase of MMP-9 showed a bimodal pattern." (PMID 34335600, 2021). "There was a strong linear relationship between the level of MMP9 and functional status in the assessed mRS scale 3 months after stroke (p < 0.001)." (PMID 33920472, 2021).
Stroke (continued). "For example, it is reported that miR-132 can directly target MMP-9 and after stroke, the reduced miR-132 expression increases MMP-9 activity which degrades TJ proteins or components of the basal lamina." (PMID 33823899, 2021). "Our data indicate that T1DM stroke rats treated with VT exhibit significantly reduced MMP9 expression and decreased numbers of M1 macrophages in the ischemic brain compared to control T1DM stroke rats." (PMID 33346402, 2021). "MMP-9 is further elevated by delayed tPA treatment and associated with exacerbated BBB breakdown during stroke." (PMID 34299322, 2021). "On an important note, stroke-induced MMP-9 expression has risen as an informative prognostic marker for a poor neurological outcome, increased mortality, and the emergence of typical signs of dementia." (PMID 34566627, 2021). "Accumulating evidence suggests that ABCB1 transporters as well as MMP-9 activity are regulated by the nuclear factor-kappa B (NF-κB) signaling pathway under non-stroke conditions." (PMID 34483846, 2021). "Elevated levels of FN1 and MMP9 predicts endothelial damage and hemorrhage after stroke in response to thrombolytic therapy." (PMID 33668216, 2021). "Studies showed that post-stroke patients presented an upregulated level of MMP9 in comparison to healthy donors, which correlated with a poorer outcome." (PMID 33920472, 2021). "Interactions of PD-1 with PD-L1 inhibit Treg-mediated neutrophil-derived MMP-9 release after stroke." (PMID 34868302, 2021). "BBB disruption resulted from tight junction protein degradation after stroke was mediated by matrix metalloproteases (MMPs), especially MMP-9." (PMID 34182541, 2021). "They identified levels of caspase-3, D-dimer, sRAGE, chimerin, secretagogin, and MMP-9 as independent predictors of stroke vs. mimics." (PMID 33633673, 2021). "While MMP-9 activity is upregulated at 48 h post-stroke, engrafted hNSCs significantly reduced MMP-9 activity." (PMID 34299322, 2021). "MMP-9 is significantly upgraded in the late phase of stroke and can lead to irreversible BBB disruption." (PMID 34576209, 2021). "Diabetic db/db stroke mice show a further increase in the MMP-9 mRNA level and activity and inflammation." (PMID 34299322, 2021). "The activation of the MMP-9 protein, which disrupts the stability of the blood–brain barrier, promotes edema and stroke progression." (PMID 34201112, 2021). "For instance, Western blot analysis shows that transplanted hNSCs attenuated MMP-9 at 48 h post-stroke, suggesting that hNSCs can reduce BBB disruption." (PMID 34299322, 2021). "Elevated systemic MMP-9 during concomitant stroke and systemic inflammation correlates with thrombolysis-associated intracerebral bleeding." (PMID 34572077, 2021). "We further studied such complexes using markers for tight-junction proteins (occludin and claudin-5) and proteases (MMP2 and MMP9) that increase the permeability of the BBB during stroke." (PMID 32221863, 2021). "Higher MMP-9 activity is correlated with BBB disruption during stroke and dysfunction of BBB tight junctions." (PMID 34299322, 2021). "Upregulation of MMP-9 by pro-inflammatory cytokines has been implicated in the disruption of the BBB during hemorrhagic transformation and ischemic brain injury in stroke." (PMID 34393790, 2021). "In our study, we found that MMP-9 expression is significantly induced, whereas MMP-2 induction is relatively limited in stroke-susceptible haplogroup F cybrids in comparison with B cybrids." (PMID 32796743, 2020). "MMP-9 levels in the ipsilateral cortex of COX-2+/+ and COX-2−/− mice were both dramatically increased after stroke, but much lower levels of MMP-9 were observed in COX-2−/− mice compared to the wild-type animals." (PMID 32973660, 2020). "Treatment with TPO also reduces stroke-induced cortical MMP-9 and TIMP-1 expression and enzymatic activity." (PMID 32341206, 2020).
Stroke (continued). "During stroke, rapid activation of the proteolytic enzyme, matrix-metalloproteinase-9 (MMP9) leads to degradation of the neurovascular unit and compromise of the blood-brain barrier (BBB)." (PMID 33505320, 2020). "Even though BR therapy profoundly protects stroke outcomes, addition of MMP-9 to the blood diminishes the protective effect of the BR therapy and substantially worsens stroke outcomes." (PMID 32843630, 2020). "The production and the upregulation of MMP-9 are extremely important in stroke development and outcome." (PMID 33362697, 2020). "Much evidence supports the function of neutrophils as a critical source of MMP-9 in the microenvironment in tumor models and perhaps more so in stroke." (PMID 32191628, 2020). "Electrochemiluminescence detection demonstrates that BR therapy reduces cytokine storm in plasma and ELISA demonstrates reduced levels of matrix metalloproteinase-9 (MMP-9) in the plasma and brains at different time points post-stroke." (PMID 32843630, 2020). "To further investigate the role of MMP-9 in the BR therapy in stroke, we designed a study of using MMP-9-treated blood compared to vehicle-treated blood for transfusion." (PMID 32843630, 2020). "It has been shown that MMP-9 inhibitors DP-b9938, KB-R778539, SB-3CT40, and BB-9437 protect stroke outcomes." (PMID 32843630, 2020). "The increase in PARP1, MMP9 and HMGB1 associated with stroke in SHRs points to the unique relationship between hypertension and the enhancement of post-stroke cell death." (PMID 33214598, 2020). "MMP-9 is increased in the blood within the first 2–6 h of stroke in patients, primates, and rodents." (PMID 32843630, 2020). "We here demonstrate the BR therapy as an effective therapeutic strategy for stroke treatment and elucidate MMP-9 involved mechanism in the therapy." (PMID 32843630, 2020). "We demonstrated increased levels of MMP-9 in the plasma obtained from tMCAO mice compared to controls at both 8 and 23 h post stroke." (PMID 32843630, 2020). "Our study is the first to show that BR therapy leads to profoundly improved stroke outcomes in mice and that the improved outcomes are mediated via MMP-9." (PMID 32843630, 2020). "Stroke induced a dramatic increase in MMP-9 enzymatic activity in the ischemic cortex, which was markedly reduced by COX-2 gene deficiency or pharmacological inhibition with CAY10404." (PMID 32973660, 2020). "First, higher MMP‐9 is involved in the neuroinflammation and blood‐brain barrier damage and correlated with post‐stroke cognitive impairment." (PMID 32431079, 2020). "Brain CD147 levels were correlated with MMP-9 and secondary hemorrhage in post-mortem samples from stroke patients." (PMID 32191628, 2020). "CD147 expression increased in human brain after stroke, which was associated with increased astrocytic CD147 expression, MMP-9 expression, and hemorrhage." (PMID 32191628, 2020). "CD147 is a major regulator of the BBB after stroke, facilitating MMP-9 mediated BBB breakdown and recruitment of peripheral leukocytes into the CNS." (PMID 32191628, 2020). "Recent study by Abdelnaseer and colleagues has shown increased MMP-9 levels during 30 days after stroke onset, which correlated with the improved patients’ clinical status." (PMID 31701356, 2020). "Taken together, these findings suggest that genetic deficiency or pharmacological inhibition of COX-2 significantly reduces stroke-induced neurovascular injury possibly by reducing MMP-9-mediated proteolysis of BBB structural components." (PMID 32973660, 2020). "In line with this notion, glutamate has been shown in pathological conditions such as stroke to exacerbate the release and recycling activity of the endothelial proteases MMP-9 and t-PA." (PMID 31392351, 2020). "The MMP-9 contributes to a wide range of biological activities in the CNS diseases, including stroke, Alzheimer’s disease, and malignant glioma." (PMID 33228717, 2020).
Stroke (continued). "Previous experimental studies have shown a neuroprotective effect of acute MMP-9 inhibition in stroke whereas MMP-9 inhibition in the early recovery phase exacerbated stroke-induced brain damage." (PMID 32300291, 2020). "It occupied the active site of MMP-9, explaining the direct effect of the compound in a stroke model." (PMID 33261005, 2020). "The expression of MMP2 and MMP9 (green) was detected by immunofluorescence assay in the IBZ of the brain on day 28 after stroke." (PMID 30947736, 2019). "Using an existing database comprising genetic details of stroke patients and controls, the team found that a major signaling pathway is inactivated and an enzyme called MMP9 is increased in stroke victims." (PMID 30911000, 2019). "The BBB disruption due to ROS production and matrix metalloproteinases (as MMP-9) is an important mechanism of brain damage in stroke." (PMID 31540440, 2019). "Of particular importance is MMP-9, also known as gelatinase B or type IV collagenase, since it has recently become a subject of growing interest in diverse human pathologies such as stroke." (PMID 30935029, 2019). "The results verified that TSP4-BMSC treatment significantly increased the secretion of MMP2 and MMP9 post-stroke." (PMID 30947736, 2019). "CaMKK inhibition enhanced MMP2 and MMP9 activity while reducing levels of key BBB proteins in adult stroke models." (PMID 31027360, 2019). "In vivo experiments performed on rat induced stroke suggested that Mv and petunidin-3-O-rutinoside (p-coumaroyl) -5-O-glucoside can be considered inhibitors of MMP-9 activity." (PMID 31261786, 2019). "In our study, based on microarray analysis and in vitro experiments, MMP9 was upregulated in stroke samples." (PMID 30911000, 2019). "They play a key role in interrupting BBB after stroke, and studies have shown that MMP-9 is overexpressed in brains suffering from cerebral ischemic lesions and that they promote brain damage and BBB failure." (PMID 31261786, 2019). "Multiple studies showed increased expression and activity of MMP-2 and MMP-9 after brain injury (such as stroke) during the recovery phase." (PMID 28290150, 2018). "In rodent models of stroke, diabetic mice have a more rapid increase in MMP-9 mRNA and protein activity post-stroke compared with controls." (PMID 29895321, 2018). "MMP-9 concentrations in the plasma were elevated both with age and after stroke, consistent with the protein levels detected in the ischemic hemisphere (SF5)." (PMID 29752550, 2018). "Relative to brain-infiltrating monocyte populations, stroke-responsive neutrophils produced more MMP-9 and ROS, and had a reduced capacity for phagocytosis which was further exacerbated with age." (PMID 29752550, 2018). "EE led to an increase in MMP-9 activity in stroke EE animals compared to stroke STD animals in the ipsilateral hemisphere (P < 0.01, 40% increase)." (PMID 28290150, 2018). "Evidence shows that the expression of zymogenic proMMP-9 is elevated and that laminin, a substrate of MMPs, is decreased in humans after stroke, with active MMP-9 seen only in patients treated with tPA." (PMID 29963617, 2018). "Due to this limitation, we cannot evaluate the effects of MMP-9 on the development of virus or bacterial meningitis in stroke and comparison cohort." (PMID 29551991, 2018). "S1RA-treated mice showed faster behavioural recovery from stroke; this finding complements the significant decreases in matrix metalloproteinase-9 (MMP-9) expression and reactive astrogliosis surrounding the infarcted cortex." (PMID 28779350, 2018). "Similar approach was used in a 30-day follow-up of stroke patients, where the serum MMP-9 concentration in the follow-up correlated positively with initial stroke severity and outcome." (PMID 29349668, 2018). "Because MMP-3 and MMP-9 are major contributors to BBB damage after stroke, we wanted to see if the reduced BBB damage evidenced by reduced IgG extravasation was associated with reduced MMP-3/MMP-9 activity and protein levels." (PMID 29527151, 2018).